LILRB1 (leukocyte immunoglobulin like receptor B1)
Diseases named in the same sentence as LILRB1 in open-access papers (continued):
Sharing a sentence is not in itself a finding about the gene and the disease.
tumor (continued). "The current results showed that the expression of LILRB1 was higher in tumor tissues compared to the matched adjacent tissues (P < 0.01)." (PMID 34485116, 2021). "Recently, it has been found that macrophages expressing inhibitory receptor LILRB1 interact with MHC class I components on the surface of tumor cells to protect tumor cells from phagocytosis." (PMID 34485116, 2021). "It was found that LILRB1 is upregulated on the surface of TAMs, and its ligand β2-microglobulin expressed by tumor cells can protect LILRB1 from being engulfed." (PMID 34771482, 2021). "For example, LILRB1 promotes tumor progression in maintaining the stem cells and hematopoietic stem cells." (PMID 34485116, 2021). "In recent years, some studies have shown that LILRB1 is expressed in a variety of tumor cells, and the expression level is significantly related to tumor growth and prognosis of patients." (PMID 34485116, 2021). "Interaction of β2M subunit of HLA-I in tumor cells with LILRB1 on macrophages protects tumor cells from phagocytosis by TAMs, and disruption of this interaction potentiates phagocytosis of tumor cells." (PMID 34447383, 2021). "The correlation between LILRB1 and clinicopathological factors, macrophage infiltration, and tumor microenvironment immune status would be analyzed." (PMID 34485116, 2021). "It has been found that LILRB1 high-expressing macrophages interact with MHC class I components on tumor cell surfaces to protect tumor cells from phagocytosis." (PMID 34485116, 2021). "We found that LILRB1 was mainly present in tumor stroma which was higher in tumor tissues compared with matched adjacent tissues." (PMID 34485116, 2021). "Blockade of the β2M/LILRB1 interaction was found to stimulate tumor cell phagocytosis by TAMs and significantly slow tumor growth in mice, representing an interesting anti-cancer immunotherapeutic approach." (PMID 32456204, 2020). "Functionally, HLA-G has comprehensive immunosuppressive properties exerted in multiple steps to weaken anti-tumor immune responses by acting on immune cells through its inhibitory receptors: ILT2(CD85j/LILRB1), ILT4(CD85d/LILRB2), and KIR2DL4(CD158d)." (PMID 32670296, 2020). "One such pathway that has been shown to impair macrophage‐mediated phagocytosis of tumor cells involves MHC class I signaling through the leukocyte immunoglobulin‐like receptor family member leukocyte immunoglobulin‐like receptor B1 (LILRB1)." (PMID 32508018, 2020). "LILRB1 may shape the tumor microenvironment of HNSCC, mediating the interactions between cancer cells and macrophages, as well as between cancer cells and CD8+ T cells, via the SPP1-CD44 and CXCL13-CXCR5 axes." (PMID 41879001, 2026). "Given its role in tumor immunity, LILRB1 is considered an atypical “immune checkpoint”." (PMID 40686307, 2025). "In melanoma, LILRB1 is enriched on tumor-infiltrating MDSCs and TAMs." (PMID 40821795, 2025). "In ovarian cancer, LILRB1 was highly expressed in both tumor cells and infiltrating immune cells." (PMID 40860159, 2025). "Thus, the HLA-G/LILRB1 axis is an important immune checkpoint not only in tumor biology but also in transplant settings." (PMID 41562090, 2025). "Importantly, RS4;11 tumor cells that relapsed following CD19 CAR-T treatment continued to express LILRB1." (PMID 40186066, 2025). "This reduced expression inversely correlated with oxidative stress markers, suggesting that oxidative stress may suppress LILRB1 to promote tumor immune evasion." (PMID 40860159, 2025). "In OC, LILRB1 is primarily expressed on immune cells (ICs) rather than tumor cells (TCs) and is strongly associated with an immunosuppressive tumor microenvironment." (PMID 40330466, 2025). "Functionally, LILRB1 promoted tumor cell proliferation, migration, and invasion." (PMID 40860159, 2025). "Thus, the combination of LILRB1 blockade with cetuximab has been tested in triple-negative breast cancer and showed significant synergistic effects in elimination of tumor cells through NK cells." (PMID 38911856, 2024).
tumor (continued). "Given that LILRB1 blockade on T cells and NK cells has been shown to enhance their tumor-killing effects, it is plausible that targeting LILRB1 in MM patients could elicit responses from both MM cells and immune cells." (PMID 38982045, 2024). "In addition, downregulation or knockout of LILRB1 can convert macrophages in order to limit tumor growth." (PMID 39003350, 2024). "Tumor expressing HLA-G family members bind to both LILRB1 and LILRB2 receptors suggesting that monotherapy blockade of either LILRB1 or LILRB2 alone could lead to tumor escape mechanisms." (PMID 39199672, 2024). "Importantly, further analysis has shown that LILRB1-expressing macrophages bears an M2- like phenotype, probably due to tumor cell mediated education through MHC1 molecules." (PMID 38911856, 2024). "In addition to NK cells, a subset of T cells expresses LILRB1 and LILRB1 blockade was shown to enhance bispecific T cell engager antibody-induced tumor cell killing by effector CD8+ T cells." (PMID 39199672, 2024). "It is possible that the effect of MM-derived LILRB1 in the immune responses and tumor cells may be different." (PMID 38982045, 2024). "In B-cell malignancies, LILRB1 may play an important role in controlling the proliferation and progression of neoplasm." (PMID 39696628, 2024). "Due to the important inhibitory function of MHC1/LILRB1 axis on innate immune cells, therapeutic disruption of this interaction may offer beneficial effects through unleashing anti-tumor innate immunity." (PMID 38911856, 2024). "Blockade of LILRB1 or LILRB2 on macrophages induces phagocytosis of tumor cells." (PMID 38785789, 2024). "By delivering LILRB1-targeting PROTACs to the tumor microenvironment, activation of T cells could be enhanced through the degradation of T cell-derived LILRB1." (PMID 38982045, 2024). "Emerging evidence also shows that LILRB1 blockade leads to anti-tumor effects through NK cells." (PMID 38911856, 2024). "To determine whether LILRB1-KD MM cells had more lipid peroxidation-induced ferroptosis in vivo, we detected the levels of lipid ROS in MM cells in the BM of tumor-bearing mice on days 7 and 15 after MM inoculation." (PMID 38982045, 2024). "Furthermore, interaction of HLA-G on the surface of tumor cells with LILRB1 on NK cells confers protection against NK cell cytolysis." (PMID 38982045, 2024). "Since β2m is a non-covalent binder to MHC1 molecules, upregulation of β2m could increase the level MHC1 complexes to interact with LILRB1 and therefore help cancer cells evade the innate immune system during tumor progression." (PMID 38911856, 2024). "Thus, LILRB1-targeting PROTACs have the potential to simultaneously enhance the immune system and promote tumor ferroptotic cell death, benefiting MM patients." (PMID 38982045, 2024). "A humanized, Fc-engineered anti-LILRB1 IgG antibody, B1-176, with reduced FcγR binding was shown to disrupt LILRB1 signaling in co-culture experiments with LILRB1 reporter cells and various tumor cell lines." (PMID 37781391, 2023). "Genes from the immune inhibitory LILRB family (LILRB1-3) are upregulated as is Versican (VCAN), which codes for epithelial to mesenchymal transition supporting proteoglycan, indicating that these cells fit the profile of tumor associated macrophages." (PMID 37532715, 2023). "However, the results were obtained with individual anti-LILRB1 antibodies, combination partners or in models of distinct tumor entities, and further studies are required to draw general conclusions." (PMID 37781391, 2023). "In addition, we found that ST6GALNAC3 was positively correlated with the immune checkpoints (SIRPA, LILRB1, SIGLEC10) of tumor associated macrophages involved in tumor antigen recognition disorders." (PMID 37138287, 2023). "LILRB1 has been demonstrated to be crucial in promoting tumor development and metastasis." (PMID 37142967, 2023).
tumor (continued). "LILRB1 ligation on tumour-associated macrophages (TAM) was shown to abrogate phagocytosis of HLA I+ tumours, which could be ablated with LILRB1 monoclonal antibodies (mAbs)." (PMID 38022598, 2023). "In addition to expression on tumour cells, higher levels of LILRB1 have been demonstrated on the peripheral blood of non-small cell lung cancer (NSCLC), renal, head and neck, oesophagus and colon cancer patients than healthy individuals." (PMID 38022598, 2023). "Expectedly, LILRB1 ligation by HLA-G on tumour cells induces tumour immune-evasion." (PMID 38022598, 2023). "Tumor volume and LILRB1 expression were shown to be significantly correlated." (PMID 37142967, 2023). "LILRB1 is also expressed by malignant cells of different tumor types." (PMID 37781391, 2023). "The knockout of its receptor LILRB1 on macrophages inhibited tumor growth." (PMID 35646915, 2022). "Therefore, combinations of tumor targeting antibodies with LILRB1 and either CD47 or SIRPα immune checkpoint inhibitors deserve further evaluation in animal models towards clinical application." (PMID 36389667, 2022). "The MHC-I/LILRB1 signaling axis is a “don’t eat me” signaling pathway, and inhibition of either LILRB1 or MHC-I may greatly enhance tumor cell phagocytosis." (PMID 35978372, 2022). "Finally, dual checkpoint blockade of CD47 and LILRB1 was tested with MCL tumor cells isolated from two patients." (PMID 36389667, 2022). "In tumor cells is a don’t eat me signal for macrophages through interaction with LILRB1." (PMID 34447383, 2021). "As an immunosuppressive receptor, LILRB1 may play a major role in the process of tumor cells escaping immune surveillance." (PMID 34485116, 2021). "The data further confirmed that LILRB1 was mainly expressed in the tumor stromal microenvironment." (PMID 34485116, 2021). "Additionally, DC express the SIRPα receptor and the leukocyte immunoglobulin-like receptor B1 (LILRB1), which, respectively, recognize CD47 and MHC class I-associated β2M subunits at the surface of tumor cells, blocking phagocytosis." (PMID 33418996, 2021). "Additionally, we also assessed the immune contexture, immune cell functions and tumor microenvironment state related to LILRB1." (PMID 34485116, 2021). "Besides, MHC class I on tumor cells directly protects them from macrophage attack through binding to the inhibitory receptor LILRB1 on the surface macrophages, which is up-regulated by tumor cells." (PMID 33224886, 2020). "In addition, therapeutic blockade of the CD24 and SIGLEC10 interaction and the MHC class I molecules and LILRB1 interaction accompanied with enhanced TAM phagocytosis towards tumor cells." (PMID 33224886, 2020). "This is consistent with our finding that NKG2C and LILRB1 expression is increased in our validation cohort, and could explain the increased activation of peripheral NK cells upon encounter with infected or tumor cells during pregnancy." (PMID 31708922, 2019). "Finally, tumor tissue samples tested positive for HLA-G and LILRB1 protein expression, and those expression levels significantly correlated with tumor stage." (PMID 27652273, 2016). "Also, blocking LILRB1 displays beneficial effects on enhancing NK cell anti-tumor activity." (PMID 39030302, 2024). "The expression of LILRB1 in the tumor microenvironment may have prognostic features." (PMID 37781391, 2023). "Moreover, there was a strong connection between tumor spread distance and LILRB1 expression." (PMID 37142967, 2023). "Therefore, it has been proposed that LILRB1 functions as an immunosuppressive receptor and may represent an attractive target to enhance tumor cell killing by effector CD8 T cells." (PMID 38053994, 2023). "Genetic deletion of HLA class I cell surface molecules augmented ADCP by anti-epithelial cell adhesion molecule (EpCAM) or anti-epidermal growth factor receptor (EGFR) antibodies, suggesting that the HLA class I:LILRB1 axis may compromise the therapeutic efficacy of tumor targeting antibodies." (PMID 37781391, 2023).
tumor (continued). "LILRB1 expression by tumor cells may have different consequences." (PMID 37781391, 2023). "Drugs targeting MHCI/LILRB1 axis may promote anti-tumor immune response and play a synergistic role with drugs targeting CD47-SIRPA axis; CD24-SIGLEC10 interaction blocks the cytoskeleton rearrangement required by macrophage phagocytosis and triggers the inhibitory signal transduction cascade." (PMID 37138287, 2023). "In addition, the antibody enhanced ADCP by the anti-EGFR antibody cetuximab in vitro, thereby providing further evidence that LILRB1 blockade may enhance the therapeutic efficacy of tumor targeting antibodies by enhancing their ADCP function." (PMID 37781391, 2023). "Interestingly the major receptor in detection and simultaneous inhibition of MHC class I triggered phagocytosis, LILRB1, was significantly upregulated and could explain a possible tumor escape mechanism." (PMID 31960110, 2020). "LILRB1 and LILRB2 are expressed in various tumor types and are recognized as immunosuppressive markers within the tumor TME." (PMID 41050411, 2025). "The expression of SIRPA, LILRB1, LILRB2, Siglec1, Siglec7, Siglec9, PDCD1, CD163 and MARCO are preferentially expressed on Mono01, Mono02 and Macro03, suggesting their tumor-promoting roles." (PMID 40755770, 2025). "LILRB1 expression was detected in over half of NSCLC samples, with levels escalating alongside advancing tumor stage 107." (PMID 40860159, 2025). "By interacting with the LILRB1, LILRB2, KIR3DL1 and CD64 receptors, it enhances anti-tumor activity." (PMID 39199672, 2024). "Knock out of LILRB1 on macrophage promoted M1 macrophage differentiation, and when combined with CD47 blockade, increased the phagocytosis of tumor cell lines." (PMID 39696628, 2024). "However, the function of tumor-derived LILRB1 in tumor biology remains unclear." (PMID 38982045, 2024). "The ability of the IOS-1002 molecule to target LILRB1 and LILRB2 receptors simultaneously is an advantage that increases the pattern of immune cell activation and decreases the likelihood of tumor resistance by receptor substitution." (PMID 39199672, 2024). "By blocking LILRB1 with BND-22, macrophages are relieved from this inhibitory signal and can effectively phagocytose tumor cells, leading to tumor regression." (PMID 38911856, 2024). "LILRB1 on immune cells was reported to bind to its ligand, major histocompatibility complex (MHC) class I subunit β2-microglobulin (B2M), on tumor cells." (PMID 38982045, 2024). "HLA-G molecules are ligands for the inhibitory immune receptors, LILRB1 and LILRB2 (also known as ILT2 and ILT4), and are frequently expressed by solid tumors, therefore, anti-HLA-G CAR-NK can both target tumor cells and relieve immunosuppression." (PMID 37388731, 2023). "The site of contact between LILRB1 on macrophages and MHC-I on tumor cells is located in the conserved α3 domain and β2M subunit rather than the highly polymorphic α1 and α2 domains of MHC-I and 1st and 2nd Ig domain of LILRB110." (PMID 36882399, 2023). "For instance, in NK cells, interaction of HLA-G and LILRB1 was shown to counteract signaling and induction of cytotoxicity by interaction of the activating NK cell receptor NKG2D with its ligand MIC A on tumor cells." (PMID 37781391, 2023). "LILRB1, located on the surface of macrophages, is recognized by MHC-I molecules and changes macrophage function from tumor growth inhibition to tumor promotion." (PMID 37958467, 2023). "Interestingly, in different studies individual LILRB1 antibodies differed in their activity to induce phagocytosis of tumor cells as single agent, which may be due to characteristics of target cells or of the antibody such as the isotype or the epitope specificity." (PMID 37781391, 2023).
tumor (continued). "Tumor cells overexpress anti‐phagocytic ligands CD47, PD‐L1 MHC‐I, and CD24, and can interact with their corresponding receptors SIRPα, PD‐1, LILRB1, and Siglec‐10 on the macrophages and send “don't eat me” signals to evade phagocytic clearance by macrophages." (PMID 37323705, 2022). "Engagement of LILRB1 and LILRB2 with its ligand HLA-G inhibits immune activation, resulting in indirect promotion of tumor development." (PMID 35321724, 2022). "M2 macrophage-derived cytokines promote an immunosuppressive tumor microenvironment, including CCL22, IL-10, and TGF-β1, that were significantly correlated with LILRB1 expression GC patients." (PMID 34485116, 2021). "We found that several pro-tumor markers are increased in cancer tissues, including CD163, CD206, SIRPα, LILRB1, SIGLEC10, AXL, MERTK, and MARCO." (PMID 34778091, 2021). "LILRB1 expression was upregulated on TAMs, disruption of either MHC class I or LILRB1 potentiated phagocytosis of tumor cells both in vitro and in vivo." (PMID 33293583, 2020). "The HLA‐I/LILRB1 pathway is often overactivated in the TME, contributing to tumor immune evasion." (PMID 40686307, 2025). "In papillary thyroid carcinoma, LILRB1 expression was significantly elevated in tumor tissues relative to matched non-tumor tissues." (PMID 40860159, 2025). "While LILRB1/2 overexpression has been observed in some cancers including AML, prostate, liver, and breast cancer, there is limited information on the functional heterogeneity of LILRB-expressing cells in the tumor microenvironment across patients." (PMID 40821795, 2025). "LILRB1 KD suppressed disease progression, which was reversed by treatment with the synthetic antioxidant, liproxstatin-1, and RSL3 was effective at reducing tumour burden in a LILRB1 KD, but not control, MM mouse models." (PMID 40853521, 2025). "LILRB1 antibody blocks the interaction of MHC-I and LILRB1 to increase the phagocytosis capability of macrophages, increase M1/M2 ratio and also improve the cytotoxic capability of both NK and T cells to inhibit tumor growth." (PMID 40835598, 2025). "Herein, we present that CAR-T cells targeted against LILRB1 specifically kill LILRB1-expressing tumor cells both in vitro and in vivo while sparing LILRB1-negative cells." (PMID 40186066, 2025). "LILRB1 can interact with MHC1 on tumor cells, forming an axis to transmit negative signals to innate immune cells." (PMID 38911856, 2024). "Contrary to LILRB1+ NK cells, the frequency of NK cells expressing T-cell immunoreceptor with Ig and ITIM domains (TIGIT), a critical inhibitory receptor correlated with NK cell exhaustion in host anti-tumor immunity, was decreased in ATB patients." (PMID 39030302, 2024). "Furthermore, when researchers knocked out leukocyte immunoglobulin-like receptor subfamily B1 (LILRB1) on the macrophage surface, which is recognized by MHC I, macrophages transition from promoting tumor growth to inhibiting it." (PMID 38273373, 2024). "Current research indicates that the inhibitory LILRB1 protein often features a common clone, GHI/75, which, when combined with anti-CD47 monoclonal antibodies, significantly boosts macrophages’ ability to engulf and kill tumor cells." (PMID 38273373, 2024). "Pre-clinical in vivo and ex vivo data for an anti-LILRB1 blocking antibody (BND-22) demonstrated a shift in the tumor microenvironment towards a more pro-inflammatory state, which translated into tumor suppression seen in different in vivo models including lung, colon and H&N cancer." (PMID 39199672, 2024). "Similarly, antibodies targeting LILRB1 and LILRB2 alone or in combination with PD-1 blockade have been shown to reinvigorate tumor immunity and are being assessed in early-phase clinical trials with encouraging initial results." (PMID 37958404, 2023). "Besides tumour cells themselves, TAMs are affected by the tumour stroma, where both CD163 and LILRB1 are present." (PMID 36900335, 2023).